GZMB (granzyme B)
Diseases named in the same sentence as GZMB in open-access papers (continued):
Sharing a sentence is not in itself a finding about the gene and the disease.
infection (continued). "Comprehensive profiling of immune responses to eukaryotic enteric viruses reveals that infection with the persistent MNV strain CR6 induces an increase in granzyme B+ CD8+ and IFN-γ+ CD8+ T cells in the colonic LP, whereas the non-persistent MNV strain CW3 does not." (PMID 39464882, 2024). "GZMB, a serine protease that activates apoptosis, has traditionally been associated with NK and CD8+ T cell killing mechanisms, explaining its increase during Tg infection." (PMID 38950025, 2024). "Interestingly, the granzyme B content of spike-specific CD8+ T cells in previously-naive individuals after omicron infection was much lower than in previously-infected individuals prior to omicron." (PMID 37604803, 2023). "Granzyme B and perforin were both increased at 24 h in the TB-stimulated cells and reduced at 48 h, suggesting that they induce apoptosis in infected cells during the early stages of infection." (PMID 37513018, 2023). "While the overall frequencies of natural killer cells (NK) were not changed in blood or BAL, the fraction and absolute number of Granzyme B + NK cells increased significantly at 2 dpi in blood, from 4 to 25% and remained elevated throughout the course of infection." (PMID 37024448, 2023). "We identified CD4+ and CD8+ memory T cells with proliferative (Ki67+) and cytotoxic functions (granzyme B+) that expanded following infection, which makes it likely that they target MAYV-infected cells." (PMID 37983245, 2023). "BCG induced the biggest GzmB+ CD4+ T cell population and the most pronounced and persistent loss of TCF-1 in all CD4+ T cells, which was evident in ~50% of the cells in the chronic phase of infection." (PMID 37122720, 2023). "In addition to IFN-γ, fully mature NK cells accumulated granzyme B in their secretory lysosomes that is critical for their cytolytic function, and its production increases during infection." (PMID 35132958, 2022). "These LAM-responsive unconventional CD8+ T-cells co-express perforin, granzyme B, and granulysin and may have a key role in infection control." (PMID 36160177, 2022). "Several studies revealed that CD8+ T-cell-derived granzyme B and TNF-α were implicated in IV-mediated lung injury, and inhibition of TNF-α signaling in CD8+ T cells markedly relieved lung injury after IV infection." (PMID 36180831, 2022). "Therefore, the decreased expression of GZMB suggests that the animals in Cluster A had a lowered host immune response to infection than the animals in Clusters B and C." (PMID 33763112, 2021). "After the first experimental infection, the mRNA transcription levels of perforin, granzyme B, INF-γ, and antiviral factor MX1 and the number of IFN-γ-releasing PBMCs when stimulated with the first challenge virus were higher in vaccinated cats compared to control cats." (PMID 34578316, 2021). "We have previously shown that NK cells upregulate GzmB after infection with ECTV." (PMID 34015056, 2021). "Thus, GPR56 does not appear to essentially contribute to TRM-cell differentiation in the Listeria-OVA infection model and the regulation of granzyme B expression in Listeria-OVA specific TRM cells." (PMID 34685654, 2021). "Also, levels of granzyme B were decreased in children with either microscopic or submicroscopic infections compared to uninfected controls whilst levels of IL-10 and IL-12p70 were comparable between infected and uninfected children." (PMID 33281757, 2020). "T cell secretion of granzyme B protects against bacterial growth in a variety of infection models." (PMID 32343740, 2020). "Consistent with their effector memory phenotype, RhCMV-specific CTLs expressed high levels of granzyme B at all timepoints analyzed, and granzyme B+ frequencies were higher in RhCMV-specific CTLs than in SIVmac239-specific CTLs during chronic SIVmac239 infection." (PMID 32922404, 2020).
infection (continued). "This may lead to increased GzmB concentration in the bacteria-containing compartment during the initial infection and therefore facilitating virulence factor degradation." (PMID 32151975, 2020). "In addition, we found that, at the initial infection stage (1 h), the bacteria are covered by fluorescently labeled GzmB indicating co-endocytosis of the enzymes together with bacteria into host cells." (PMID 32151975, 2020). "In addition, in children with submicroscopic infections, IL-12p70 correlated negatively with IL-10 (r = -0.52, p = 0.012), whereas, granzyme B correlated positively with IL-4 (r = 0.62, p = 0.002)." (PMID 33281757, 2020). "Also, total numbers of CD8+ GzmB+ T cells in the lung tissue was significantly higher in Mavs−/− mice at day 8 during primary infection." (PMID 33123150, 2020). "Lethal IOE infection was also associated with increased numbers of hepatic non-resident macrophages producing granzyme B (nearly 9%) compared to uninfected mice." (PMID 31575880, 2019). "However, GCV did not significantly impact (p = 0.19) CD8+gp33+ T cells to secrete granzyme B in response to the LCMV‐Arm infection." (PMID 31148373, 2019). "Importantly, Cxcr3−/− OT-I T cells are not inherently defective in becoming bystander-activated as we observed granzyme B expression at later time points when the infection had become systemic." (PMID 31676770, 2019). "H-1PV infection alone and in combination with both checkpoint inhibitors caused strong activation of CTLs, which was reflected by an increased number of CD8+GranB+ cells and increased release of granzyme B, IFNγ, and TNFα." (PMID 31192129, 2019). "However, in BM the numbers of CD8+ CD43+ GzmB+ cells remained enhanced in both KO mouse strains at most of the later time points after infection." (PMID 30804928, 2019). "Interestingly, however, the functionality of NK cells 24 h after LCMV Cl13 infection was altered, with Il27ra-−/− NK cells showing reduced granzyme B and increased IFN-γ production compared to WT NK cells." (PMID 29593047, 2018). "A recent comparison of monkey species in which SIV infection is either pathogenic or non-pathogenic found higher GzmB expression in CD4 T cells from pathogenic rhesus macaques (pathogenic infection) compared to African green monkeys (non-pathogenic infection)." (PMID 28167943, 2017). "In contrast, in the infected TLR2/9−/− mice, the high level of granzyme B could be contributing to an exacerbated immune response and the pathogenesis of the infection, contributing to animal death." (PMID 28222752, 2017). "Thus, we examined the cytolytic potential of CD38+ CD4+ T cells by measuring their intracellular expression of perforin and granzyme B by flow cytometry both prior to and at peak infection." (PMID 27662621, 2016). "Both IFNγ expression in CD4+ and CD8+ T cells as well as Granzyme B expression in CD8+ T cells peaked on day seven post infection which was consistent with the expression of CD11a and KLRG1 on CD8+ T cells, demonstrating that these cells were antigen-experienced effector cells." (PMID 27875529, 2016). "The frequency of cells expressing perforin or granzyme B was significantly greater in CD38+ CD4+ T cells than in CD38- CD4+ T cells prior to and post infection (p = 0.001 and p = 0.011 prior to infection, and p = 0.012 and p = 0.017 at peak infection for perforin and granzyme B, respectively)." (PMID 27662621, 2016). "Granzyme B expression gradually decreased as the infection proceeded." (PMID 27760221, 2016). "Additionally, the CD38+ CD4+ T cells contained a higher proportion of cells co-expressing perforin and granzyme B (p = 0.001 and p = 0.006 prior to and at peak infection, respectively." (PMID 27662621, 2016).
infection (continued). "Peripheral blood CD8 T cells were activated (determined by Ki67 and CD38 expression) in response to infection and expressed perforin, granzyme B, HLA-DR, PD-1, T-bet and Eomes together with low levels of Bcl-2 at day 7 after hospitalization, phenotypically defining these as effector cells." (PMID 25611738, 2015). "Later on in infection, at week 10, the increase in the mRNA levels of Tbet, GATA3 and RORγC paralleled the reduction in expression levels of the Treg-associated molecules Foxp3, PD-L1, CCR5, CCR6 and Granzyme B." (PMID 26512987, 2015). "Additionally, we found that G1(+) animals expressed higher levels of GZMB in NK cells during early infection." (PMID 25418588, 2014). "However, poly(I∶C)-pretreated P14 CD8 T cells had substantially lower levels of granzyme B expression than control-treated cells at day 5 post infection." (PMID 25255454, 2014). "Here we show that at early stages of Brucella infection a heterogeneous effector T cell population including CD8+ CTLs and CD4+CTLs both expressing high levels of Granzyme B is present in the spleen and LNs, whereas CD4+Granzyme B- IFN-γ+ T cells develop at later stages of the infection." (PMID 24367519, 2013). "However, activated CD8+ T cells from the livers of mice receiving IV rAd infection also fail to produce IFN-γ or granzyme B in response to the in vitro stimulation with PMA/ionomycin (J.R. Lukens, unpublished observations)." (PMID 19876399, 2009). "In addition, rOnCTRP9 enhanced the ability of T cells to produce Granzyme B during infection." (PMID 41249580, 2025). "Additionally, neutrophils upregulate GZMB upon infection, leading to the secretion of granzyme B, which contributes to extracellular matrix remodeling and the disruption of endothelial junctions, thereby facilitating neutrophil extravasation and tissue migration." (PMID 41316271, 2025). "Furthermore, immunization with the model antigen NP-OVA or sheep red blood cells failed to upregulate GzmB in either CD8+ or CD4+ T cells, whereas infection with the vaccinia virus Western Reserve strain (VACV) induced GzmB expression in a subset of both CD4+ and CD8+ T cells." (PMID 37161048, 2023). "Since the inducible expression of TNF-α, IFN-γ, and Granzyme B are highly associated to T-cell cytotoxicity, our results implied that TGF-β1 might inhibit the effector function of tilapia T cells to eliminate pathogenic infection." (PMID 36581209, 2022). "Nonetheless, we observed that NKp46+, CD8+, and GZMB+ cells are significantly more prevalent in virus-infected lungs compared to bacterial infection, which reinforces our model that urinary signatures generated by host cell responses vary based on infection etiology." (PMID 35696579, 2022). "In vitro Puumala orthohantavirus infection of PBMC caused MAIT cell CD69 upregulation, and infection of MAIT cells in co-culture with the monocyte cell line THP-1 induced upregulation of CD69, CD38 and CD25, as well as the markers of cytolytic capacity perforin, granzyme B and CD107a." (PMID 35381137, 2021). "Finally, a significantly smaller frequency and number of CD8αloCD11ahi CD8 T cells responding to ZIKVBR infection were positive for expression of the key cytolytic molecule granzyme B than those responding to ZIKVCDN infection, suggesting they have reduced cytolytic capacity." (PMID 34193875, 2021). "The probably less efficient co-endocytosis of uncharged trypsin might therefore explain our result that the presence of trypsin during the infection impairs intracellular Listeria growth less efficiently than GzmB, although it is proteolytically more active in cleavage assays." (PMID 32151975, 2020). "Although Tem cells are less proliferative and could not persist for a long term, they are ready to provide immediate protection at infection sites via producing multiple cytotoxic molecules, including granzyme B (Gzmb), perforin, interferon gamma (IFNγ), tumor necrosis factor (TNF), etc.." (PMID 32983095, 2020).
infection (continued). "However, bacterial factors essential for adhesion and invasion, such as the Salmonella invasion proteins SipA and SipC or the mycobacterial Heparin-binding hemagglutinin (HbhA), were cleaved very efficiently, pointing again toward a defect early during infection in response to GzmB." (PMID 32151975, 2020). "Thus, the observed differences regarding granzyme A/granzyme B vs. CD107a/perforin abundances might be a result of complex ligand/receptor binding events induced early on during infection leading to discrete maturation of lytic granules in NK cells." (PMID 32038647, 2019). "Here, we show for the first time that TLR3 modulate the infection against Paracoccidioides brasiliensis by dampening pro-inflammatory response, NO production, IFN+CD8+T, and IL-17+CD8+T cell activation and cytotoxic function, associated with granzyme B and perforin down regulation." (PMID 30687643, 2018). "Also in INT-407 cells, Ras related nuclear protein (RAN) signaling, caveolar-mediated endocytosis, tRNA charging and granzyme B signaling were induced only at earlier stages of infection, while remodeling of epithelial adherens junction and phagosome maturation were induced only at later times." (PMID 28491823, 2017). "Interestingly, GzmB expression was also triggered by AdGFP infection lacking the cognate antigen but was more pronounced upon AdOVA infection, indicating that antigen-specific restimulation was superior to virus-induced inflammation in augmenting GzmB expression." (PMID 26404698, 2015). "Importantly, double cytokine-deficient mice did not display enhanced GzmB nor Prf1 protein levels following infection." (PMID 26720279, 2015). "These cells expressed IL-10, IL-17, perforin, granzyme B, PD-1, and CD39/CD73 when restimulated with SARS-CoV-2 peptides, suggesting a unique suppressive Treg signature that persists even after the infection is resolved." (PMID 41488664, 2025). "These functions act synergistically with the cytotoxic CD8+ TEM, which, upon viral reactivation, migrate to infection sites, secrete IFN-γ and TNF-α, and eliminate infected cells through granzyme B-mediated cytotoxicity." (PMID 41425559, 2025). "Following 1e5 PFU infection, at 3 dpi in the liver, PEP-R619W M-cNK cells (CD11b+ CD49b+ CD49a− NK1.1+) have higher expression of (i) IFNγ, (ii) T-bet, (iii) granzyme B, and (iv) perforin, compared to PEP-WT M-cNK cells (i–iv)." (PMID 40791464, 2025). "Intriguingly, after 24 h of HSV-1dko-GFP infection, there was a promotion of CD8-positive CAR-T cells, along with an increase in granzyme B secretion." (PMID 38953982, 2024). "Following infection, the respiratory tract recruits SARS-CoV-2–specific CD4+ and CD8+ T cells, a substantial proportion of which release the cytotoxic substance granzyme B (GzB)." (PMID 39178263, 2024). "All NK subsets in both PBMC and BAL upregulated granzyme B at day 3 in response to SARS-CoV-2 infection and had mostly returned to baseline levels by 4–5 weeks post-infection." (PMID 38950078, 2024). "We also measured the production of granzyme B in the PBMCs of HVL and healthy individuals after infection with cGLP LdCen1−/− parasites." (PMID 38918456, 2024). "Since bystander-activated CD8+ T cells are known to secrete cytotoxic molecules including granzyme B and express NKG2D to drive protection against unrelated pathogens, we evaluated these markers from days 1 to 7 after infection." (PMID 36951943, 2023). "IL-12 and -18 induce IFN-γ production, possibly contributing to early infection control, whereas IL-15 equips memory CD8+ T cells to produce cytotoxic molecules like granzyme B and perforin." (PMID 36951943, 2023). "PD-1+ TOX+ CD8+ T cells isolated from the site of infection produced significantly less IFN-γ, TNF-α and Granzyme B than their PD-1- TOX- CD8+ T cell counterparts after T. cruzi-specific stimulation ex vivo." (PMID 35720419, 2022).
infection (continued). "In particular, CD8+ T cells exhibit a high proportion of CD57+ terminal effector cells, together with significant decrease of naïve cell population, augmented granzyme B and IFN-γ production and unresolved inflammation 6 months after infection." (PMID 35757700, 2022). "Surprisingly, E. granulosus s.s. infection resulted in increased IL-10 expression in hepatic or splenic CD8+ T cells from CD4 knockout mice and decreased granzyme B or IFN-γ expression." (PMID 36046744, 2022). "Later during infection, type I IFN activities influence T cells with the induction of cytokine secreting CD4+ T cells and the stimulation of Granzyme B (GzmB) and IFNγ expression by cytotoxic CD8+ T cells." (PMID 36325470, 2022). "Only 3 (IRS1, MEF2c, and GZMB) out of 29 miRNA predicted mRNA targets showed statistically significant expression changes (FC > 2; FDR < 0.05) in SARS-CoV-WT versus ΔE infection." (PMID 35229638, 2022). "We also observed an increased frequency of GranzymeB (GzmB) positive total CD8+ T cells in the lungs of dKO mice compared to WT mice at four- and ten-days post-infection." (PMID 35477960, 2022). "Consistent with human data, both strains of IAV induced early MAIT cell activation with marked increase of granzyme B expression by day 3 and upregulation of the activation markers CD25 and CD69 peaking at day 5 post infection." (PMID 35381137, 2021). "The same study also showed in patients with severe infection a high frequency of cytotoxic CD4 T cells, that express perforin and granzyme B (GrB), including cytotoxic Tfh." (PMID 34630382, 2021). "Data from human studies and animal models have highlighted ex vivo granzyme B production as a distinguishing feature of virus-specific effector CD8+ T cells that have recently encountered antigen in vivo, through either infection or vaccination." (PMID 33400687, 2021). "At fourteen days post infection, MA24 showed increased expression of Granzyme B in both the DP and CD8 T cell populations." (PMID 34929014, 2021). "Neither RhCMV-specific CTL population exhibited significant changes in frequency, memory phenotype, granzyme B expression, exhaustion marker (PD-1 and CTLA-4) expression, or polyfunctionality between pre- and chronic SIVmac239 infection timepoints." (PMID 32922404, 2020). "From 4 to 10 weeks post-infection, the levels of IFN-γ, granzyme b, and perforin in NK cells from the liver decreased, and the level of IFN-γ in NK cells from the spleen decreased significantly." (PMID 33330140, 2020). "After infection, specific CD8+ T cells increase granzyme B expression when compared to CD8+ T cells from naïve group." (PMID 32574175, 2020). "From 2 to 4 weeks post-infection, levels of IFN-γ, granzyme b, and perforin in NK cells from the liver and spleen increased significantly." (PMID 33330140, 2020). "Following secondary infection (re-challenge), CTLA4Ig combined with MI not only markedly suppressed memory recall, but also led to a stronger inhibition of IFN-g or Granzyme B secreting CD8+ T cells." (PMID 32328063, 2020). "Consistently, the ICS data presented substantial attenuation of Granzyme B, CD107, and IFNγ production in Tcf7−/− CD8 T cells compared to WT CD8 T cells at both day 8 and day 25 after Cl13 infection." (PMID 30814995, 2019). "We found that both subsets increase production of granzyme B and IFN-γ and show improved degranulation during infection." (PMID 31921133, 2019). "Once at their site of infection, TEM cells express granzyme B. Expression of granzyme B, however, is downregulated in TCM cells." (PMID 30894857, 2019). "In contrast, at day 12 after infection the numbers of transferred virus-specific CD8+ T cells and the numbers of cells producing of GzmB were similar in both groups of mice." (PMID 30804928, 2019). "During the acute phase of the infection, increased expression of CD69, CD38, Ki67, and granzyme B was observed on NK cells indicating activation." (PMID 31156653, 2019).